IL27 (interleukin 27)
Diseases named in the same sentence as IL27 in open-access papers (continued):
Sharing a sentence is not in itself a finding about the gene and the disease.
melanoma (continued). "In addition, we found that IL27 could enhance the therapeutic efficacy of immunotherapy for melanoma." (PMID 34733272, 2021). "Functionally, elevated IL27 expression could induce an enhanced immune response and pyroptosis (R = 0.64, P = 1.2e-55), autophagy (R = 0.37, P = 7.1e-17) and apoptosis (R = 0.47, P = 1.1e-27) in patients with melanoma." (PMID 34733272, 2021). "In addition, IL-27 inhibited in vitro and in vivo growth of prostate cancer cells and tumor angiogenesis and also triggered anti-angiogenic responses through the induction of anti-angiogenic chemokines in mouse melanoma models." (PMID 26657115, 2015). "The cooperative effect could be ascribed to the augmented expression of TLR3, but not retinoic acid-inducible gene-I or anti-melanoma differentiation-associated gene 5, by IL-27." (PMID 24155891, 2013). "In addition, in various tumor models, including C26 colon carcinoma cells, Lewis lung carcinoma, TBJ neuroblastoma, and B16F10 melanoma cells, tumor cell lines genetically engineered to overexpress IL-27 showed growth inhibition, in vivo, compared to the IL-27-negative parental cell lines." (PMID 24130734, 2013). "In addition, in in vitro experiments using human melanoma cell lines, we showed that IL-27 can induce the expression of IL-10 and, more consistently, that of PD-L1 in these cells, suggesting that an autocrine loop may operate in these cases." (PMID 24130734, 2013). "We then examined whether IL-27 induces IRF-1 expression in these human melanomas." (PMID 24155891, 2013). "To analyze whether IL-27-mediated PD-L1 induction on melanoma cells could have an immunosuppressive effect, we performed co-culture experiments in which A375 cells were pre-treated or not with IL-27 for 15 hrs before incubation with PBMC and CD3/CD28 beads for 3 days." (PMID 24130734, 2013). "In addition, elevated IL27 expression could induce an enhanced immune response and pyroptosis (R = 0.64, p = 1.2e−55), autophagy (R = 0.37, p = 7.1e−17), and apoptosis (R = 0.47, p = 1.1e−27) in patients with melanoma." (PMID 36713514, 2022). "PSA enhanced metastatic potential of mouse melanoma B16F1 cells and increased β-hexosaminidase activity in an IL-27-dependent manner." (PMID 34234781, 2021). "For example, IL-27 was shown to act on Sca-1+c-Kit+ cells in bone marrow and promoted their differentiation into M1 macrophages in preclinical mouse studies of B16F10 melanoma and MC38 colon adenocarcinoma." (PMID 33418929, 2021). "The levels of IL-6, IL-8, IL-10, IL-17A, IL-27, IL-31, GM-CSF, IFN-α, IL-9, VEGF-D, TNF-β, NGFβ, IL-23, IL-22, and IL-1α were below the threshold of detection in both melanoma patients and healthy controls." (PMID 33574842, 2021). "IL27 has been reported to play dual roles in cancer; however, its effects on the tumor microenvironment (TME), immunotherapy, and prognosis in melanoma remain largely unclear." (PMID 34733272, 2021). "This study was aimed to uncover the effects of IL27 on TME, immunotherapy and prognosis in patients with melanoma." (PMID 34733272, 2021). "To further demonstrate the cooperative effect between IL-27 and poly(I:C), we examined the effect of the combination on TRAIL expression in human melanomas." (PMID 24155891, 2013). "Among the three melanoma cell lines, SK-MEL-37 cells expressed the highest TRAIL mRNA amount after stimulation by IL-27." (PMID 24155891, 2013). "Our data also concur with studies that used IL-27-transduced cancer cell lines, including colon carcinoma, TBJ neuroblastoma and B16F10 melanoma, which showed that induced IL-27 expression, from tumor tissue itself, enhanced the protective immune response." (PMID 23554861, 2013). "We here show that IL-27 enhances the expression of TNF-related apoptosis inducing ligand (TRAIL) and TLR3 in human melanomas and therefore inhibits their tumor growth in cooperation with poly(I:C) partly in a TRAIL-dependent manner." (PMID 24155891, 2013).
melanoma (continued). "Taken together, these results suggest that IL-27 enhances the expression of TRAIL and TLR3 in human melanomas and inhibits their tumor growth in cooperation with poly(I:C), partly in a TRAIL-dependent manner." (PMID 24155891, 2013). "In three different human melanoma cell lines, SK-MEL-13, -28, and -37, IL-27 induced tyrosine phosphorylation of STAT1 and STAT3, indicating that these cells were responsive to IL-27." (PMID 24155891, 2013). "IL-27 enhanced the expression of TRAIL mRNA, and the presence of poly(I:C) further augmented it in all three melanomas." (PMID 24155891, 2013). "We previously demonstrated that IL-27 induces IRF-1 expression, which is involved in the inhibition of tumor growth, in mouse melanoma B16F10 cells ectopically expressing WSX-1." (PMID 24155891, 2013). "Furthermore, IL-27 has the potential to interact with novel therapeutics; it synergizes with poly(I:C), a TLR3 agonist, to reduce proliferation of melanoma and prostate cancer cells via TRAIL or TLR3, respectively." (PMID 31681561, 2019). "Moreover, human melanoma cells, which constitutively express WSX1, showed growth inhibition by IL-27." (PMID 28255204, 2017). "As expected, the AML cell line, HL-60, and the melanoma cell line, A375, with little expression at cell surface of either gp130 or IL-27R did not respond to IL-27 stimulation (data not shown)." (PMID 27119567, 2016). "Human melanomas were treated with increasing concentrations of IL-27 in the presence or absence of poly(I:C) for 24 h, and resultant cells were harvested." (PMID 24155891, 2013). "We previously demonstrated that IL-27 induces IRF-1 expression in mouse B16F10 melanoma cells ectopically expressing wild-type WSX-1, but not in those expressing WSX-1 mutated in the tyrosine residue critical for STAT1 binding." (PMID 24155891, 2013). "The murine B16F10 melanoma cell line used in mouse models does not express the IL-27Rα chain and does not respond to IL-27." (PMID 24130734, 2013). "Three human melanoma cell lines were treated with increasing doses of IL-27 in the presence or absence of poly(I:C)." (PMID 24155891, 2013). "IL-27 inhibited tumor growth of melanomas, while anti-TRAIL Ab, but not control Ab, partly but significantly abrogated the inhibitory effect by IL-27 on tumor growth in all three melanoma cell lines." (PMID 24155891, 2013). "We previously demonstrated that mouse melanoma B16F10 cells are not responsive to IL-27 due to a lack of expression of one of the IL-27R subunits, WSX-1." (PMID 24155891, 2013). "Second, although this study showed IL27 could serve as an independent predictor of survival outcomes of melanoma patients from the TCGA cohort, we did not validate this in another cohort due to a lack of such datasets with complete clinical information." (PMID 34733272, 2021). "Similarly to our studies the serum level of IL-27 did not correspond with metastatic disease as it was shown in the example of melanoma." (PMID 34283046, 2021). "Thus, although IL-27 positivity was not restricted to a specific stage of melanoma, it was found in a higher proportion of advanced primary melanomas (19/23 cases of stages 3 and 4) compared to early lesions (9/20 cases of stages 1 or 2)." (PMID 24130734, 2013). "Thus, as observed in nevus, no substantial amounts of IL-27 were detected in melanoma in situ." (PMID 24130734, 2013). "These melanomas expressed TRAIL-R1 and TRAIL-R2, and the expression levels appeared not to be affected by IL-27." (PMID 24155891, 2013).
Autoimmunity (32 papers, 2008 to 2025). The occurrence of an immune reaction against the organism's own cells or tissues. "In the context of autoimmunity, IL-27 has been implicated in both pro- and anti-inflammatory responses." (PMID 30906912, 2018). "Because IL-27 has been implicated in the mechanism of IFN-β- mediated suppression of autoimmunity and Th17 cell responses we investigated the mRNA expression of IL-27p28 in MOG91–108-stimulated spenocytes from pMOG-, pMOG-IFNbeta- or pCI-treated rats." (PMID 18997868, 2008). "In this review, we comprehensively summarized information about IL-27 and autoimmunity based on available evidence." (PMID 38566992, 2024). "IL-27 is an IL-12 family cytokine with immune regulatory properties, capable of modulating inflammatory responses, including autoimmunity." (PMID 36725904, 2023). "The compositions and roles of five IL-12 family cytokines (IL-12, IL-23, IL-27, IL-35, and IL-39) in inflammation or autoimmunity have been characterized." (PMID 34782759, 2022). "In contrast to IL-12 and IL-23, IL-27, and IL-35 are related to the development of regulatory T (Treg) cells, which can suppress inflammation and control autoimmunity." (PMID 34782759, 2022). "So far, a physiological role of IL-27 production by DC was shown to prevent autoimmunity in the central nervous system by inhibiting Th17 development and promoting Treg generation, via the induction of CD39 expression." (PMID 30787928, 2019). "Interleukin-27 (IL-27) plays an important role in regulation of anti-inflammatory responses and autoimmunity; however, the molecular mechanisms of IL-27 in modulation of immune tolerance and autoimmunity have not been fully elucidated." (PMID 30483251, 2018). "The elevation of serum IL-27 concentrations in CJ IgM (+) group also indicates an inflammatory role in antimicrobial function and autoimmunity." (PMID 29434217, 2018). "For the potential therapeutic use of IL-27, previous in vivo and in vitro studies have shown that IL-27 can be used as an anti-tumor or anti-viral agent as well as a modulator of autoimmunity." (PMID 22827855, 2012). "In the context of autoimmunity, the overlapping EAE phenotypes of IL-27, IL-10, and IFNAR deficient mice suggest that these molecules are probably functionally linked in the regulation of Th17 development." (PMID 22163016, 2011). "Additionally, IL-27 restrains the expansion and activation of effector T cells, thereby preventing immune-mediated tissue damage and autoimmunity." (PMID 39766196, 2024). "All this information showed that IL-27 has played significant roles in autoimmunity." (PMID 38566992, 2024). "Based on those explanations and the results of several studies about the altered expression of IL-27 in autoimmunity and skin disorders, it was hypothesized that the concentration of IL-27 in vitiligo patients might be altered." (PMID 32616337, 2020). "IL-27 exerts potent anti-inflammatory effects in both infection and autoimmunity." (PMID 33101289, 2020). "Furthermore, tolDCs exert some of their effects through the cytokine IL-27 that has been identified as a key inducer of Tr1 and inhibitor of Th17 during autoimmunity." (PMID 31732775, 2019). "Therefore, IL-27 (acting on Tr1 cells) plays a critical role in controlling autoimmunity, providing a putative target therapy." (PMID 31732775, 2019). "Our data suggest that IL-27-treated mature DCs may block autoimmunity through upregulation of CD4+CD127+3G11+ Tregs development in vivo." (PMID 30483251, 2018). "Interestingly, the experimental data also indicate that IL-27 is an anti-inflammatory cytokine and inhibits development of autoimmunity in vivo." (PMID 30483251, 2018). "Our results also suggest that IL-27 may promote autoimmunity toward pancreatic islets via the upregulation of the STAT1 pathway." (PMID 28248954, 2017).
Autoimmunity (continued). "IL-27 suppresses effector Th17 cells and promotes the generation of type 1 regulatory T (Tr1) cells, which, in turn, could dampen autoimmunity and tissue inflammation by secreting the immunosuppressive cytokine IL-10." (PMID 26636339, 2015). "Therefore, the present study, using IL-27 in a gene therapy protocol, provides evidence that supports its potential effectiveness in autoimmunity." (PMID 22827855, 2012). "Importantly, IL-27 receptor-deficient (IL27RA–/–) mice have been shown to develop exaggerated pro-inflammatory T-cell responses and autoimmunity, suggesting that IL-27 to also inhibits tissue inflammation, possibly via induction of type 1 regulatory cells (Tr1) cells." (PMID 33717163, 2021). "Another study reported that the levels of IL-27 and IL-23 increased significantly in the serum and urine of systemic lupus erythematosus patients with and without lupus nephritis compared with healthy control, which may account for the pleiotopic roles of IL-27 in several cases of autoimmunity." (PMID 32849596, 2020). "IL-27 was shown to be a key regulator of IL-10 and IL-17 production by human CD4+ T cells thus providing a dual regulatory mechanism to control autoimmunity and tissue inflammation." (PMID 25698903, 2015). "IL-27 can act as both pro-and anti-inflammatory cytokine, however, molecular mechanisms of IL-27 to modulate autoimmunity and immune tolerance have not yet been fully elucidated." (PMID 30483251, 2018). "To further address the in vivo relevance of Ch25h in inducing IL-27-driven TR1 cells and the potential effect on regulating autoimmunity and tissue inflammation, we conducted repeated in vivo treatments with anti-CD3 to induce IL-10+ regulatory T cells, that have been shown to be IL-27 dependent." (PMID 28993775, 2017). "Treg cell suppression by IL‐27 may lead to tissue damage by CD8+ T cells and/or the development of autoimmunity involving CD4+ T cells, and thus both can increase patient susceptibility toward exacerbation." (PMID 24994897, 2014). "As a pro-inflammatory cytokine, IL-27 activates T helper 1 (TH1) responses in the early phases of immunity, in which secretion of interferon-gamma (IFN-γ) is one of the key inflammatory mediators in autoimmunity." (PMID 22827855, 2012). "Besides the induction of PD-L1 expression in tumor cells, IL-27 may have additional immune-suppressive activities through the induction of IL-10-producing or PD-L1-expressing regulatory-type CD4+ T cells, such as described in autoimmunity and GVHD models." (PMID 34439164, 2021). "Lack of suppression of ongoing autoimmunity by AAV-IL-27 is consistent with the report showing that IL-27 could not inhibit established Th17 responses, but appears to be inconsistent with other reports demonstrating that systemic IL-27 inhibits T cell adoptive transfer EAE." (PMID 29740452, 2018).
Arthritis (30 papers, 2010 to 2025). Inflammation of a joint. "In arthritis-susceptible Lewis rats that were injected with IL-27, there was reduced expression of IL-17, RORγt, IL-23, and IL-6 in arthritic joints, and the joint space was clear with minimal MNC infiltration of the synovial tissue." (PMID 38566992, 2024). "Thus, by preventing osteoclastogenesis, IL-27 can prevent bone degradation caused by arthritis." (PMID 39766196, 2024). "Indeed, IL-27 has been implicated in the pathogenesis of RA, though has also shown protective effects against experimentally-induced arthritis in murine models." (PMID 31280933, 2019). "It has been shown that the inhibition of the interleukin 27 (IL‐27) pathway dampens TH17‐rich TLSs in early arthritis." (PMID 40910751, 2025). "For example, in a rat model of arthritis, neutralizing antibodies against IL-27 significantly inhibited inflammatory factor production and alleviated arthritis symptoms." (PMID 39906735, 2024). "For instance, in mice with CIA, the local production of IL-27 utilizing intra-articular injections of an adenoviral vector resulted in a decrease in the histological and clinical signs of arthritis." (PMID 39766196, 2024). "WT rats injected with complete Freund’s adjuvant had severe clinical features of arthritis, and the addition of IL-27 antagonist downregulated villous hyperplasia, infiltration of the inflammatory cells, pannus formation, and angiogenesis." (PMID 38566992, 2024). "The current status of IL-27 delivery in arthritis models includes its evaluation in a mouse model of CIA, where it ameliorated inflammation following local delivery via adenovirus." (PMID 35735491, 2022). "In vivo, in a murine model of collagen-induced arthritis, IL-27 induced Th1 differentiation and IFNγ secretion constraining osteoclast differentiation." (PMID 35479090, 2022). "first explored the role of IL-27 in arthritis mice and found that arthritis in IL-27-treated collagen-induced arthritis (CIA) mice was relieved." (PMID 35058928, 2021). "Due to the distinct pathogenesis and pleiotropy of IL-27, the responses of different arthritis animal models are diametrically opposed." (PMID 35058928, 2021). "Evidence from animal studies suggests that IL-27 exerts pro- or anti-inflammatory roles in different arthritis animal models." (PMID 35058928, 2021). "IL-27 is a therapeutic under development by our group for arthritis and malignant tumors, on the basis of its multifunctional (immune stimulatory, anti-angiogenic, pro-osteogenic) activity." (PMID 32046108, 2020). "IL‐27 is expressed in synovial macrophages, and increased levels of IL‐27 relieve arthritis in CIA mouse ankles." (PMID 32530555, 2020). "Taken together, our data show that IL-27 negatively regulates IL-23-induced arthritis by decreasing the expansion and motility of neutrophils and by reducing γδ T cells during arthritis development." (PMID 29765156, 2018). "Another study confirmed the presence of IL-27 in the spleen and joint tissues of a proteoglycan-induced arthritis (PGIA) model." (PMID 29879214, 2018). "Similar to these observations in our data overexpression of IL-27 also inhibited arthritis initiation and progression." (PMID 29765156, 2018). "It has been reported that IL-27 can accelerate the progression of arthritis by promoting Th1 cell generation; however, IL-27 can also alleviate arthritis by suppressing Th17 responses." (PMID 28612255, 2017). "IL-27 is a proinflammatory factor which is involved in the pathogenesis of many human inflammatory diseases, such as psoriasis, arthritis, and asthma." (PMID 24659862, 2014). "Using a murine model, IL-27 can exhibit a suppressive effect on inflammation and can attenuate collagen-induced arthritis when administered at the onset of the disease via the blocking of Th17 differentiation from naïve T helper cells." (PMID 20604932, 2010). "In animal studies of RA, administration of IL-27 can attenuate collagen-induced arthritis at the disease onset stage in mice." (PMID 20604932, 2010).